EGFR (epidermal growth factor receptor)
Diseases named in the same sentence as EGFR in open-access papers (continued):
Sharing a sentence is not in itself a finding about the gene and the disease.
melanoma (continued). "Cloudman S91 clone M3 mouse melanoma cells were transduced with lentiviral particles carrying the human EGFR gene followed by a multistep selection process." (PMID 36432639, 2022). "In a follow-up study, the same group reported that NRF2 regulates EGFR expression via binding to an ARE in its promoter region in melanoma cells." (PMID 35326683, 2022). "It warrants future clinical studies targeting the AhR‐dependent SRC/FAK/EGFR axis in combination with BRAFi/MEKi double blockade to re‐sensitize melanoma to standard melanoma treatment and counteract resistance." (PMID 36305167, 2022). "In the present study, we developed a Cloudman melanoma S91 clone M3 cell line demonstrating preserved expression of human EGFR both in vitro and, most importantly, in vivo in immunocompetent mice." (PMID 36432639, 2022). "Representative cancer-related genomic information includes epidermal growth factor receptor (EGFR) mutation in non-small cell lung cancer (NSCLC), ABL1 gene recombination in chronic myelogenous leukemia (CML), and BRAF mutations in melanoma." (PMID 35893795, 2022). "In melanoma cells, the expression of receptor tyrosine kinases such as EGFR, PDGFRB, and ERBB3 increases upon exposition to BRAF/MEK inhibitors." (PMID 35565444, 2022). "Another receptor tyrosine kinase, Xrmk, was identified as closely related to EGFR, and therefore involved in melanoma development and progression; in detail, Xrmk has been studied in Xiphophorus platyfish and in zebrafish as a therapeutic target." (PMID 35713744, 2022). "To sum up, we successfully developed the first mouse syngeneic melanoma model with preserved in vivo expression of human EGFR." (PMID 36432639, 2022). "There are numerous EGFR-expressing human cancer cell lines, including melanoma ones which are successfully used for in vitro screening of the EGFR-targeted agents being developed." (PMID 36432639, 2022). "The aim of this study was the development of a syngeneic mouse melanoma tumor model for testing anti-cancer agents targeted at human EGFR, and we made progress in this direction." (PMID 36432639, 2022). "The involvement of proteins regulating EGFR in melanoma resistance indirectly proves the role of this receptor in response to targeted therapies." (PMID 35565444, 2022). "For instance, human epidermal growth factor receptor (EGFR) signaling was implied when PLD c GMP analog protein kinase G activator 5 (PA5) was injected into zebrafish melanoma models, thus targeting the cGMP/protein kinase G pathway." (PMID 35713744, 2022). "HER2 can form functional dimers with HER3/ERBB3 or with EGFR, both of which were also found to be enriched in MVs from melanoma cells with supernumerary centrosomes." (PMID 36875714, 2022). "The assessed number of receptors was 13,900 ± 1500 per cell, which lies within the typical range (8 × 103–3 × 105 receptors per cell) of EGFR expression in human melanomas." (PMID 36432639, 2022). "EGFR is a member of the RTK family and upregulated EGFR promotes migration and invasion of melanoma cells." (PMID 35610275, 2022). "To test the effect of STING ADCs in vivo, we used a mouse tumor model in which the C57BL/6J mice were implanted subcutaneously with B16F10 melanoma cells stably expressing human EGFR (B16-EGFR)." (PMID 36442099, 2022). "Activation of EGFR will stimulate melanoma cells to progress or metastasize and be resistant to BRAF inhibitors." (PMID 34745259, 2021). "Here, we describe that NRF2 is also involved in maintaining the EGFR-expressing subgroup of melanoma cells." (PMID 33916908, 2021). "In summary, NRF2 enhances EGFR activity by inducing the expression of EGFR and its ligands in melanoma, with EGF transcription being directly regulated by NRF2." (PMID 33916908, 2021). "A more recent analysis of melanoma brain metastases detected high frequency of EGFR amplification in metastases overall but the highest in the brain." (PMID 34885093, 2021).
melanoma (continued). "HB-EGF promotes melanoma growth through its interaction with EGFR and in its role as a MAPK and PI3K/Akt pathway activator." (PMID 34360915, 2021). "A recent study demonstrated that treatment of ECs with melanoma cell-derived exosome enhanced VE-Cadherin, uPAR, and EGFR upregulation in ECs, resulting in a tumor EC phenotype, and through EGFR gave EGFL7 a chance to promote neoangiogenesis." (PMID 33804387, 2021). "This feedback leads to one important difference in response to treatment between melanoma and CRC: BRAF(V600E) inhibition causes a rapid feedback activation of EGFR, which supports continued proliferation." (PMID 33507915, 2021). "The insight into regulators of EGFR expression and activation is important for the understanding of the development of this malignant melanoma phenotype." (PMID 33916908, 2021). "The receptor tyrosine kinase epidermal growth factor receptor (EGFR) is found in a subtype of melanoma with a poor prognosis and contributes to drug resistance." (PMID 34360915, 2021). "EGFR is well studied in melanoma and has been found to activate autophagy and melanoma cell mobility." (PMID 34809598, 2021). "The receptor tyrosine kinase EGFR is activated in a subset of melanoma cells where its expression correlates with poor prognosis in human melanoma." (PMID 34360915, 2021). "KRAS, an EGFR-induced cell signaling downstream mediator, has been found to be mutated in about 25% of Non-small cell lung cancer (NSCLC) cases, whereas in melanoma, KRAS mutations are rare and found in only 1.7% of the cases." (PMID 33807778, 2021). "In summary, our data indicate that the antitumor effects in melanoma of ALOC-EO are driven by the blockade of EGFR signaling." (PMID 34360915, 2021). "Study indicated that DBH-AS1 can increase glycolytic activity in melanoma cells, thus disrupting melanoma progression through miR-223-3p/EGFR/AKT axis." (PMID 33517850, 2021). "In a melanoma xenograft model, cancer cells expressed very little EGFR, and targeting endothelial EGFR with TKI sufficiently retarded tumor growth." (PMID 34680445, 2021). "Because EGFR signaling promotes melanoma cell proliferation, and ALOC-EO targets EGFR signaling, we assessed the proliferation-inhibitory effects of ALOC-EO on EGFR OE cells or cells treated with rec." (PMID 34360915, 2021). "In contrast to SOX10, RUNX2 can increase the expression of several receptor tyrosine kinases including EGFR in melanoma." (PMID 33916908, 2021). "Alternatively, in BRAF inhibitor-resistant human melanoma cell lines, there is pronounced hypomethylation of the EGFR gene promoter, leading to increased expression of EGFR and metastasis through PI3K/Akt signaling." (PMID 34067095, 2021). "As EGFR pathway activation is so strongly connected to BRAF/MEK inhibitor resistance in melanoma, it is likely that stress-induced NRF2 activation during therapy significantly contributes to this effect." (PMID 33916908, 2021). "Together, these results suggest that Lrg1 promotes melanoma cell migration and invasion by activating the EGFR/STAT3 signalling pathway in a Src-independent manner." (PMID 34208965, 2021). "Melanoma or non-small cancer cells, among other cancer cells, acquire drug resistance by upregulating EGFR after BRAF exposure." (PMID 34360915, 2021). "Recent studies demonstrated that EGFR signaling contributes to a more malignant phenotype in melanoma-treated cells after chemotherapy." (PMID 34360915, 2021). "PRDX6 is upregulated in human melanoma cells, increases cell proliferation by activating Src signaling via the production of arachidonic acid, and its expression depends on EGFR signaling." (PMID 34067095, 2021). "In summary, NRF2 initiates a mechanism that leads to the maintenance of melanoma cells with high EGFR and low MITF levels, where NRF2 and EGFR pathways enhance each other in a positive feedback loop." (PMID 33916908, 2021).
melanoma (continued). "Overall, our study provided strong evidence of Lrg1’s role in melanoma metastasis and Lrg1 exerting its function through activation of the EGFR/STAT3 signalling pathway." (PMID 34208965, 2021). "Here, we describe that the transcription factor NRF2, the master regulator of the oxidative and electrophilic stress response, mediates the expression and activation of EGFR in melanoma by elevating the levels of EGFR as well as its ligands EGF and TGFα." (PMID 33916908, 2021). "While 22 was particularly more cytotoxic against MCF-7/topo cells, most probably due to EGFR-targeting, complex 23 demonstrated a specific anti-melanoma activity, possibly dependent on the Akt/mTOR signaling pathway." (PMID 34070457, 2021). "As expected, inhibition of sirtuin 2 activities resulted in a decrease in EGFR levels, confirming our previous observation that this sirtuin regulates EGFR gene expression in melanoma cells." (PMID 34068624, 2021). "A similar effect was obtained with a peptide that inhibits uPAR–EGFR interaction and with the EGFR inhibitor Gefitinib, which also inhibited melanoma Exos-dependent EGFR phosphorylation." (PMID 33237352, 2021). "Our results revealed for the first time that silencing the OPN gene influences proliferation and invasion of melanoma cells by effecting EGFR, tenascin C, survivin, galectin-3 and enolase 2 expression." (PMID 34257527, 2021). "The knockout of this tumor suppressor gene in BRAF mutant melanoma cells triggered senescence and apoptosis through overactivation of the EGFR‐MAPK pathway." (PMID 33955157, 2021). "To better understand this mechanism, we exploited in the present study two melanoma cell lines, genetically identical but expressing different levels of uPAR and EGFR." (PMID 34055629, 2021). "In a study addressing the function of the transcription factor Nuclear Factor Erythroid 2 Like 2 (NFE2L2 or more common NRF2) in melanoma, we observed that EGFR is strongly reduced after NRF2 knockdown." (PMID 33916908, 2021). "Conversely, EGF led to the nuclear localization and activation of NRF2, thereby demonstrating that NRF2 and EGFR are connected in a positive feedback loop in melanoma." (PMID 33916908, 2021). "The biologically regulated pathways with significantly different changes in PSRSA vs NRSA involved cytokine‐cytokine receptor interaction, MAPK signalling pathway, melanoma and EGFR tyrosine kinase inhibitor resistance." (PMID 34132454, 2021). "RAS-directed melanoma tumor maintenance in vivo had been shown to depend on a functionally relevant EGFR autocrine loop." (PMID 34360915, 2021). "At the post-translational level, tyrosine kinase ACK1, which is downregulated in some BRAF inhibitor-resistant melanomas, induces EGFR turnover." (PMID 33916908, 2021). "Expression of EGFR in melanoma establishes a pro-metastatic phenotype that can activate Ras/MAPK, PLCγ1/PKC, Akt, and STAT, which subsequently stimulate cell proliferation, migration, invasion, survival, and differentiation." (PMID 34360915, 2021). "As the effect of the drug on pSRC was rather minimal (data not shown), we decided to assess other signaling pathways downstream of EGFR, which are crucial for melanoma cell survival, including pAKT, pcRAF and pERK1/2." (PMID 34068624, 2021). "We find that LRIG1 is downregulated during early tumorigenesis and that LRIG1 affects activation of the epidermal growth factor receptor (EGFR) in melanoma cells." (PMID 33947959, 2021). "uPAR is expressed in melanoma Exos that are internalized by HMVECs and ECFCs, enhancing VE-Cadherin, EGFR and uPAR expression in endothelial cells that undergo a complete angiogenic program, including proliferation, migration and tube formation." (PMID 33237352, 2021). "Knockdown of FUT4 in melanoma cells also resulted in decreased Lewisy expression and reduced EGFR phosphorylation, and inhibited melanoma cell proliferation through EGFR-mediated MAPK signaling pathway." (PMID 34069424, 2021).
melanoma (continued). "Medaka expressing HER-mrk, which exhibits invasive melanoma, has been used to show that activated Xmrk induces EGFR expression and ligand production leading to the formation of an autocrine loop that promotes pro-tumorigenic signaling." (PMID 34067095, 2021). "The myelosuppressive drugs upregulated HB-EGF and EGFR in melanoma cells in a dose-dependent manner." (PMID 34360915, 2021). "In summary, our data show that the EGFR-positive melanoma phenotype is strongly supported by NRF2, thus revealing a novel maintenance mechanism for this clinically challenging melanoma subpopulation." (PMID 33916908, 2021). "MITF and EGFR are expressed in melanoma cells in a mutually exclusive manner, and MITF was described previously to suppress TGFA expression." (PMID 33916908, 2021). "For example, up to half of melanoma cases have been found to harbour activating mutations at BRAF V600, while EGFR mutations have been found to be present in over 30% of NSCLCs." (PMID 34441338, 2021). "The results confirmed that APOL1 have higher expression in GSE46517 while ATG16L2, DAPK2, ATG9B and EGFR have lower expression in GSE15605 for primary melanoma compared with normal skin." (PMID 34809598, 2021). "Our study demonstrated that LRG1 regulates multiple aspects of melanoma metastasis through modulating EGFR/STAT3 signalling." (PMID 34208965, 2021). "EGFR plays a role in melanoma initiation in murine models, while its role in human melanoma is less clear." (PMID 34281234, 2021). "The inhibition of Janus kinase 1 (JAK1) activity due to ubiquitination by RNF125 decreased EGFR expression at the transcriptomic and protein levels, overcoming BRAFi resistance in melanoma cells." (PMID 33800394, 2021). "The compounds were screened against a panel of EGFR(+) (MCF-7/topo multidrug resistant breast adenocarcinoma) and EGFR(−) (518A2 melanoma, HL-60 leukemia, and KB-V1/Vbl cervix cancer) cancer cell lines." (PMID 34070457, 2021). "Below, we will discuss the aim and therapeutic effect of each of the tested small molecule EGFR inhibitors in melanoma." (PMID 33918490, 2021). "This combination (foretinib “MET inhibitor”and lapatinib or gefitinib) showed synergistic effect in different melanoma cells with different levels of RTK (cells express EGFR and MET)." (PMID 33918490, 2021). "Our results fully proved that RA played a role of protecting melanoma cells against malignant metastasis by inhibiting ADAM17/EGFR/AKT/GSK3β axis." (PMID 34224305, 2021). "Another report showed that Rg3 inhibits melanoma cell growth through inhibition of EGFR phosphorylation and FUT4/LeY downregulation in vitro and in vivo." (PMID 34440905, 2021). "Several melanoma models support the pro-metastatic role of EGFR, as it enhances cellular migration as well as angiogenesis." (PMID 33916908, 2021). "In an effort to determine the clinical relevance of the findings above in vivo, the relationship between GLI1/2, MITF, and EGFR was determined in the TCGA melanoma cohort." (PMID 34572373, 2021). "The positive effect of NRF2 on EGFR levels was confirmed in two independent EGFR-positive melanoma cell lines, where the extent of EGFR reduction notably correlated with the efficiency of the NFE2L2 knockdown." (PMID 33916908, 2021). "In line with this, we previously showed that EGFR expression in melanoma models triggers oncogene‐induced senescence in the absence of drugs but becomes beneficial in the presence of BRAF or MEK inhibitors." (PMID 33955157, 2021). "Here, we review the comparative genomic characteristics of the human EGFR and fish Xmrk receptor systems and the implications of this information for Xmrk oncogenic signaling in melanoma and HCC." (PMID 34067095, 2021). "EGFR gene copy number alterations and polysomy of chromosome 7—where the EGFR gene is located—are correlated with poorer prognosis in human melanoma." (PMID 34360915, 2021).
melanoma (continued). "In conclusion, our study demonstrated that LRIG1‐TG mice develop melanocytic skin tumors during chemical skin carcinogenesis and a deletion of LRIG1 in human melanoma cells reduces EGFR and ERBB3 expression after EGF stimulation." (PMID 33786987, 2021). "While elevated EGFR expression has been previously found in melanomas resistant to vemurafenib, for the first time we have shown that an enhancement of EGFR expression and activity can be associated with the development of resistance to trametinib." (PMID 31936151, 2020). "Similar to the melanoma cases, these genes tended to be involved in cytokine signalling pathway, adaptive immune system, and EGFR signalling in cancer." (PMID 32075964, 2020). "In another study, BRAF V600E expressing malignant melanoma cells with resistance to RAF inhibitors showed activation of the EGFR/PI3K/AKT pathway." (PMID 32046099, 2020). "Mechanistically, Gal-1 sustains increased expression of NRP1 and EGFR in drug-resistant melanoma cells." (PMID 32784465, 2020). "The aim of this study was to check possible correlations between hyperprogression to checkpoint inhibitors and amplification (≥4 copies) of MDM2, MDM4 or EGFR in acral and mucosal melanoma." (PMID 32110946, 2020). "Short treatment of melanoma cells with BRAF inhibitors has led to either augmented EGFR protein level as the result of epigenetic regulation or increased phosphorylation of the baseline EGFR." (PMID 31936151, 2020). "The Ras–MAPK pathway is frequently deregulated in tumours arising from epithelial tissues (e.g. carcinomas and melanoma) as a result of genetic alterations and upstream activation of cell surface growth factor receptors (e.g. EGFR)." (PMID 32601464, 2020). "By using preclinical model, it was proven that EGFR inhibition enhanced the antitumor effect of vemurafenib in BRAF-mutant human melanoma." (PMID 32613561, 2020). "We have presented evidence for the inactivation of TFEB and ZKSCAN3 by the co-effect of CAP and SN and blockage of the mTOR/EGFR pathway that provides a compelling model to explain the suppression of melanoma and resultant autophagy-lysosome activation." (PMID 32178401, 2020). "FAN1 was the most common germline mutation gene in our cohort, of which 27 variations were found, followed by the genes EGFR, ERBB2, and MSH3, which were found mutated 20 times in melanomas of our study." (PMID 32083130, 2020). "Nevertheless, in BRAFi-resistant EGFR overexpressing melanoma cells, EGFR is functional but usually inactive." (PMID 32605090, 2020). "Here, we confirm that Gal-1 controls EGFR upregulation in drug-resistant melanoma cells via a NRP1-dependent mechanism." (PMID 32784465, 2020). "Genes positively or negatively correlated with PLK1 were mainly assembled in pathways such as DNA replication, cell cycle, mismatch repair, Ras signaling pathway, melanoma, EGFR tyrosine kinase inhibitor resistance and homologous recombination (P < 0.05)." (PMID 33354424, 2020). "Epigenetic changes affecting epidermal growth factor receptor (EGFR) have been shown to also induce the PI3K-Akt pathway in melanoma resistant cells." (PMID 32092958, 2020). "A previous study of EGFR inhibitors and sodium arsenite combination treatment reportedly induced both apoptotic and necrotic events in melanoma cells." (PMID 32002123, 2020). "Five key genes FLG, DSG1, DSG3, IVL, and EGFR were identified in the TCGA database and melanoma tissues." (PMID 33178610, 2020). "It was previously reported that NRP1 negatively controls the expression of p27/Kip1 cyclin-dependent kinase inhibitor in cancer cells, a mechanism required to unleash the pathway leading to EGFR upregulation in PLX-resistant melanoma cells." (PMID 32784465, 2020). "The inhibitor NT157 has also been shown to increase the tyrosine-phosphorylation 1172 at EGFR in the melanoma cell line A375." (PMID 32667922, 2020).